DUSP14 (dual specificity phosphatase 14)
Description:
Involved in the inactivation of MAP kinases. Dephosphorylates ERK, JNK and p38 MAP-kinases. Plays a negative role in TCR signaling by dephosphorylating MAP3K7 adapter TAB1 leading to its inactivation.
Synonyms: MKP-L; MKP6
Tractability: PROTAC: ubiquitination databases record sites on it.
Target class: Phosphatase; Serine/threonine/tyrosine protein phosphatase; Enzyme; Protein Phosphatase
Gene: Protein-coding gene on chromosome 17 (37,488,397 to 37,513,517, forward strand). Ensembl gene ENSG00000276023.
Subcellular location (Human Protein Atlas): Cytosol; Nucleoplasm
Gene Ontology:
Molecular function: protein binding; protein serine/threonine phosphatase activity; RNA binding; MAP kinase tyrosine/serine/threonine phosphatase activity; protein tyrosine phosphatase activity
Genetic constraint (gnomAD): Loss-of-function variants: 5 observed, 13.72 expected, observed/expected ratio (o/e) 0.36, 90% interval 0.19 to 0.77. The upper end of that interval is the gene's LOEUF score, 0.77, which puts it in group 3 of 6, group 1 being the genes least tolerant of losing a copy. Missense variants: 185 observed, 277.65 expected, observed/expected ratio (o/e) 0.67, 90% interval 0.59 to 0.75. Synonymous variants: 91 observed, 108.11 expected, observed/expected ratio (o/e) 0.84, 90% interval 0.71 to 1.
Homologues: Orthologues: chimpanzee DUSP14 (100% identical), macaque DUSP14 (99% identical), pig DUSP14 (99% identical), dog DUSP14 (98% identical), rabbit DUSP14 (98% identical), guinea pig DUSP14 (97% identical), rat Dusp14 (95% identical), rat Dusp14l1 (94% identical), mouse Dusp14 (94% identical). Paralogues in human: DUSP18 (46% identical), DUSP21 (43% identical), SSH2 (34% identical), DUSP16 (32% identical), DUSP1 (32% identical), DUSP4 (31% identical), DUSP13B (30% identical), DUSP26 (30% identical), DUSP8 (30% identical), SSH1 (30% identical), SSH3 (30% identical), DUSP5 (29% identical), and 19 more.
Diseases named in the same sentence as DUSP14 in open-access papers:
DUSP14 is named in the same sentence as 31 diseases in open-access papers, as found by Europe PMC text mining. Sharing a sentence is not in itself a finding about the gene and the disease. The quoted sentences say what the papers report.
autoimmune disease (3 papers, 2019 to 2026). A disorder resulting from loss of function or tissue destruction of an organ or multiple organs, arising from humoral or cellular immune responses of the individual to their own tissue constituents. "Therefore, enhancement/activation of DUSP14 or DUSP14 upstream molecules is a potential modality for the attenuation of autoimmune diseases such as systemic lupus erythematosus (SLE)." (PMID 37849501, 2023). "Therefore, enhancement/activation of DUSP14 or DUSP14 upstream molecules may lead to the treatment or attenuation of autoimmune diseases." (PMID 31766293, 2019). "Besides autoimmune diseases, reduction of DUSP1, DUSP2, and DUSP14, as well as induction of DUSP8 contribute to the pathogenesis of allergic diseases." (PMID 42087139, 2026). "In addition, DUSPs are also involved in either human autoimmune diseases (DUSP2, DUSP7, DUSP10, and DUSP12) or T-cell activation (DUSP1, DUSP5, and DUSP14)." (PMID 31766293, 2019).
breast cancer (3 papers, 2012 to 2019). A primary or metastatic malignant neoplasm involving the breast. "miR-9 and miR-155 levels are higher in metastatic breast cancer-derived exosomes and the two miRNAs downregulate the expression of PTEN and dual specificity protein phosphatase 14 (DUSP14) in recipient cells." (PMID 31355262, 2019). "Dusp14 is a MAPK phosphatase responsible for dephosphorylating ERK, JNK, and p38, and thus, of extreme importance as a downstream signal in the IGF-1 pathway in regulating mammary tumor growth." (PMID 23342276, 2012).
diabetes (2 papers, 2020 to 2022). "Upregulation of CDK2, the CDC25A phosphatase and DUSP14 in diabetes-free tumors is consistent with the tumor phenotype as these genes are reportedly overexpressed to stimulate cell proliferation and invasion in CRC." (PMID 32971867, 2020).
glioma (2 papers, 2015 to 2024). A benign or malignant brain and spinal cord tumor that arises from glial cells (astrocytes, oligodendrocytes, ependymal cells). "The identification of MYBL2, RBM6, VEPH1, AHNAK2, GNG10, and DUSP14 as key genes offers valuable insights into the molecular mechanisms underpinning glioma progression and its interaction with COVID-19." (PMID 39684661, 2024). "In our model high expression of DUSP6 and DUSP14 is predictive of resistance to paclitaxel in melanoma and glioma." (PMID 26274927, 2015).
Hepatic steatosis (2 papers, 2022 to 2023). Steatosis is a term used to denote lipid accumulation within hepatocytes. "DUSP14 significantly ameliorates HFD-mediated or genetically induced insulin resistance, hepatic steatosis, and concomitant inflammation." (PMID 36823220, 2023). "According to our current findings, previous studies, and the characteristic of DUSPs family, we demonstrated that the dephosphorylating capacity of DUSPs family members (DUSP22, DUSP3, DUSP9, DUSP12, DUSP14, DUSP26, etc) might be indispensable for its protective role against hepatic steatosis." (PMID 36209205, 2022).
ischemia (2 papers, 2022 to 2025). A hypoperfusion of the BLOOD through an organ or tissue caused by a PATHOLOGIC CONSTRICTION or obstruction of its BLOOD VESSELS, or an absence of BLOOD CIRCULATION. "Moreover, hepatic ischemia–reperfusion injury reduced Dusp14 expression, which suggests that Dusp14 is a protective factor in liver damage." (PMID 35401113, 2022). "Genes associated with the stress-activated MAPK pathway—such as Dusp3, Dusp10, Dusp14, Junb, and Fos—were also specifically upregulated after ischemia, which may enable astrocytes to manage heightened stress signals, regulate inflammatory responses, and initiate repair mechanisms." (PMID 40618091, 2025).
melanoma (2 papers, 2015 to 2022). A malignant, usually aggressive tumor composed of atypical, neoplastic melanocytes. "A further analysis of MAPK regulatory genes showed that mRNAs for several DUSPs-DUSP1 DUSP5, DUSP8, DUSP10 and DUSP14-were upregulated in intrinsically MAPKi-resistant melanoma cell line." (PMID 35999349, 2022).
Autoimmunity (1 paper, 2019). The occurrence of an immune reaction against the organism's own cells or tissues. "Two atypical DUSPs, MKP-6 (DUSP14) and JKAP (DUSP22), are linked to T cell activation and autoimmunity." (PMID 31297117, 2019).
breast tumor (1 paper, 2022). "For example, highly metastatic breast tumor cell-derived exosomal miR-9 and miR-155 can induce metastasis in non-metastatic cells via targeting phosphatase and tensin homologue (PTEN) and dual specificity protein phosphatase 14 (DUSP14), respectively." (PMID 35592419, 2022).
cardiac failure (1 paper, 2023). "DUSP14, a member of the DUSP family, can protect the heart against cardiac failure." (PMID 37647434, 2023).
Cognitive impairment (1 paper, 2021). Abnormal cognition is characterized by deficits in thinking, reasoning, or remembering. "For instance, DUSP14 protects against isoflurane-evoked inflammatory response and cognitive impairment in aged rats." (PMID 34605731, 2021).
ischemic stroke (1 paper, 2021). A stroke disorder caused by obstruction of blood flow to the brain, due to thrombotic (local blood clot formation) or embolic (due to a blood clot or other material traveling from another site) event. "Analogously, DUSP14 may act as a potential therapeutic target to prevent ischemic stroke by attenuating cerebral apoptosis." (PMID 34605731, 2021).
liver fibrosis (1 paper, 2022). "Among all these analyzed DUSPs, DUSP3, DUSP8, DUSP12, DUSP14, DUSP16, DUSP22, and DUSP26 were significantly decreased in the liver of NASH patients with obvious hepatocyte ballooning, severe inflammatory infiltrate, and pattern of liver fibrosis compared with the normal individuals." (PMID 36209205, 2022).
lung carcinoma (1 paper, 2017). "Knockout of DUSP14, and that of ITCH or CYLD promotes progression of EAE and lung cancer, respectively, accompanied with sustained activation of TAK1 signaling." (PMID 28106845, 2017).
myocardial ischemia (1 paper, 2022). A disorder of cardiac function caused by insufficient blood flow to the muscle tissue of the heart. "DUSP14 knockout mice after myocardial ischemia–reperfusion injury induce the activation of MAPKs, including elevated p-p38, p-ERK1/2, and p-JNK in heart tissues." (PMID 35401113, 2022).
non-alcoholic fatty liver disease (1 paper, 2022). "It is reported that DUSP14 knockout aggravated pathological processes involved in non-alcoholic fatty liver disease development, whereas DUSP14 overexpression ameliorated these pathological alterations." (PMID 35401113, 2022).
osteoarthritis (1 paper, 2021). A noninflammatory degenerative joint disease occurring chiefly in older persons, characterized by degeneration of the articular cartilage, hypertrophy of bone at the margins and changes in the synovial membrane. "Although this research provides some new clues to the function of DUSP14 in osteoarthritis progression, there are some deficiencies as well as limitations to this study." (PMID 34605731, 2021).
psoriasis (1 paper, 2022). An autoimmune condition characterized by red, well-delineated plaques with silvery scales that are usually on the extensor surfaces and scalp. "In keratinocytes, previous studies have shown that the expression of DUSP2 and DUSP5 changed in response to an adalimumab treatment in psoriasis patients whereas arsenic, a human carcinogen that can cause squamous cell carcinomas (SCCs), could inhibit the expression of DUSP2 or DUSP14." (PMID 36080217, 2022).
tumor (6 papers, 2017 to 2024). "Among upregulated genes in PDOs derived from basal-like tumors were genes that have been associated with tumor progression or cell survival including BAG3 (log-rank p = 0.0015), DUSP14 (log-rank p = 0.014), and LYPD3 (log-rank p = 0.013)." (PMID 39363341, 2024). "miR-9 and miR-155 target PTEN (phosphatase and tensin homologue) and DUSP14 (dual specificity phosphatase 14) tumour suppressor genes in MCF-7 cell lines extracted from MDA-MB-231 exosomes." (PMID 36838790, 2023). "Moreover, the expression levels of ATF3 in CRC correlated with the expression of its target genes, such as CEACAM1, DUSP14, HDC, HLF and ULBP2, which are required for tumor cell invasion and proliferation and are robustly linked to poor prognosis in CRC." (PMID 28402947, 2017). "In addition, upregulated HDC and dual-specificity phosphatase 14 (DUSP14) are molecules that are related to cell adhesions with a low expression in the early stage of CRC, thus they act as tumor suppressors." (PMID 28402947, 2017).
cancer (5 papers, 2016 to 2023). A tumor composed of atypical neoplastic, often pleomorphic cells that invade other tissues. "In the immune system, DUSP14 negatively regulates β cell proliferation and apoptosis of cancer cells." (PMID 35401113, 2022). "The first eight of the nineteen targets, PIAS3, p27, RAB10, DBF4, DUSP14, RBPMS, PDPN and CLTC, were considered to be closely associated with cancer progression after a literature review." (PMID 28120918, 2017). "DUSP14 is an important negative regulator of the mitogen-activated protein kinase (MAPK) signaling pathways, which are involved in inflammatory response, cancers, cell proliferation and differentiation." (PMID 28402947, 2017). "Our results reveal an unexpected role of PA reprogramming induced by dephosphorylation of ACOX1 in activating β-catenin signaling and promoting cancer progression, and propose the inhibition of the dephosphorylation of ACOX1 by DUSP14 or β-catenin palmitoylation as a viable option for CRC treatment." (PMID 36878899, 2023).
infection (3 papers, 2015 to 2021). The state of being infected such as from the introduction of a foreign agent such as serum, vaccine, antigenic substance or organism. "In order to elaborate the function of DUSP14 in osteoarthritic chondrocyte function, the expression of DUSP14 was enhanced after LV-DUSP14 infection." (PMID 34605731, 2021). "Moreover, knocking down DUSP14 expression via siRNA in murine macrophages resulted in a lower bacterial load 90 hours post-infection with MTB H37Rv80." (PMID 26586179, 2015). "Yet, DUSP14 was upregulated at 18 hours post-infection with MTB H37Rv (q-value: 16%), MTB GC1237 (q-value: 3%), and BCG (q-value: 9%); and downregulated post-infection with S. typhimurium (q-value: 9%)." (PMID 26586179, 2015). "In our joint Bayesian analysis, DUSP14 was not classified as one of the genes whose regulation was altered in response to infection with mycobacteria." (PMID 26586179, 2015).
DUSP14 also shares sentences with these, for which no sentence is quoted: cardiac hypertrophy (2 papers); allergic disease (1); COVID-19 (1); Hearing Defects (1); hearing loss (1); Insulin resistance (1); neurological diseases (1); squamous cell carcinoma (1); systemic lupus erythematosus (1); tuberculosis (1).